FN1 (fibronectin 1)
Diseases named in the same sentence as FN1 in open-access papers (continued):
Sharing a sentence is not in itself a finding about the gene and the disease.
tumor (continued). "FBN1, FN1, HGF, MMP9, THBS1, and VCAN may be new GC prognostic targets by affecting tumor purity, TMB, TME score, and multiple oncogenic signaling pathways." (PMID 33014013, 2020). "Individual contributions of the two phenotypes in “heterogeneous” tumours resulted in major changes in cell–cell junctions and ECM interactions with increased expression of FN1, TNC and matrix re‐modellers, and alterations in the repertoire of collagens and adhesion receptors." (PMID 32145051, 2020). "Finally, we determined that LGALS3, CD44, FN1 and EZR were upregulated in both tumour and host stromal datasets." (PMID 32493768, 2020). "Proto-oncogenes are those genes that are involved in cell growth and proliferation, with potential examples including the ATM, FGFR2, FN1, IGF1, MAP3K, MMP7, and RHOC genes, while the CASP8 and LSP1 genes have been reported to possess tumor-suppressive properties in certain types of cancer." (PMID 33112566, 2020). "In addition, Muc1 was downregulated, while Fn1 and Itga5 were upregulated in PDC compared to classical tumours." (PMID 31439856, 2019). "FN1 expression was evaluated in the tumor stroma component, localized to non-malignant fibroblasts and extracellular matrix." (PMID 30736807, 2019). "The tumor ECM is composed of a complex mixture of macromolecules, including fibrous proteins (collagen, ELN), proteoglycans (heparan sulfate, chondroitin sulfate), glycosaminoglycans (hyaluronic acid), and glycoproteins (FN1, laminins, TNC)." (PMID 31106200, 2019). "We suggest that PLA2R1-regulated expression of FN1, TWIST1, and CDK6 might be accountable for the cell type-dependent impact of PLA2R1 in tumour cell survival and growth." (PMID 30542512, 2018). "Overall, these findings imply that blockade of the FN1/SPP1-ITGAV pathway may inhibit the seeding and consequently the metastasis of tumor cells in fibrotic lungs." (PMID 27329720, 2016). "In addition to blocking VEGFR2, YLL545 altered the expression of other molecules involved in tumor angiogenesis, including ITGAV, ENG, THBS1, FN1, and TEK." (PMID 27203384, 2016). "Of note, while TGFB1, a master regulator of the malignant phenotype, appeared to be mostly up-regulated in the tumour, its activators THBS1, FN1 and ITGA4 were strongly induced in tumor cells and ECs, highlighting a concerted molecular interaction to regulate cellular activity." (PMID 27049916, 2016). "Moreover, the CM-FLF-induced apoptosis resistance or chemotaxis of tumor cells was attenuated when ITGAV, the common receptor of FN1 and SPP1, was silenced by RNA interference or blocked by GRGDS treatment in tumor cells." (PMID 27329720, 2016). "Furthermore, the serum deprivation-triggered apoptosis was increased when tumor cells were cultured in the conditioned medium from the FN1 and SPP1-silencing fibroblasts, and this effect was more prominent when both FN1 and SPP1 were silenced in fibroblasts." (PMID 27329720, 2016). "Herein, we revealed that a non-classical chemokine FN1 was increased in fibrotic lungs and chemoattracted tumor cells in vitro, thus at least partly contributed to the enhanced seeding of tumor cells in fibrotic lungs." (PMID 27329720, 2016). "FN1 functionally connects a pair of coexpressed glycoproteins, FBLN1 and FSTL1, and SPARC is connected to IGFBP7, a tumor suppressor, which creates a functional link between a candidate tumor suppressor, PDGFRL, and a mesenchymal factor, FSTL1." (PMID 24944582, 2014). "Thus, tumor thickness, mitotic rate, tumor vascularity, RGS1 expression level, and FN1 expression level were uniformly potent predictors, with positive weights in all of the three subgroups." (PMID 23460802, 2013). "Notably, LEF1 was identified as a regulator of FN1 and CDH1 expression in tumor-derived cells and was proposed to act in both, a CTNNB1-dependent as well as -independent manner." (PMID 23677615, 2013).
tumor (continued). "The EIIIA and EIIIB regions are absent in plasma FN1 and EIIIA/EIIIB containing FN1 is poorly expressed in normal adult tissue but overexpressed in developing embryos, wound healing and tumours." (PMID 19126199, 2009). "A group of genes, including collagen type I alpha 1 (COL1A1), fibronectin 1 (FN1), laminin subunit gamma 2 (LAMC2), periostin (POSTN), transforming growth factor beta induced (TGFBI), are involved in extracellular mesenchymal organization and affect tumor behavior, akin to our findings." (PMID 40303998, 2025). "The differential interactome composition indicates a functional shift in EGFR signaling that may drive increased tumor cell adhesion (CD44, ITGB1, FN1), metabolic adaptation (GAPDH, ENO1) and stress response (HSPA4, HSP90AB1), consistent with mechanisms observed in therapy‐resistant CRC phenotypes." (PMID 41319168, 2025). "FN1-mediated interactions showed significant bi-directional communication across these cell types, suggesting ECM-driven adhesion and structural organization at the Pseudo.A-MVP boundary, consistent with FN1’s involvement in matrix remodeling and tumor-stroma integration." (PMID 41366031, 2025). "Interestingly, a significant correlation was found between the expression of TGF-β and IL-6 expression in primary CRC tumor and FN1 in the metastatic intrahepatic tumor but not the local primary CRC tumor." (PMID 40335453, 2025). "Thirdly, although the function of FN1 was validated through in vitro experiments utilizing Caov-3 and SK-OV-3 cell lines, these findings may not adequately reflect the in vivo tumor microenvironment." (PMID 40612060, 2025). "In our study, the upregulation of the FN1 signaling pathway between CCL18+ macrophages and endothelial cells, particularly in the non-responder group, indicated their potential role in promoting endothelial cell proliferation and tumor angiogenesis in NSCLC patients." (PMID 38730286, 2024). "We detected 24 genes across the tumor tROIs that showed a high CV (i.e., were among the genes with the top 20% highest CV in seven out of seven cases), such as multiple collagens (COL1A1, COL1A2, COL3A1, COL5A1, COL5A2), S100A8, S100A9, FN1, or Early growth response protein 1 (EGR1)." (PMID 37511126, 2023). "Additionally, inhibition of fibronectin 1 (FN1), involved in cell adhesion, migration, and invasion of cancer cells, could suppress tumor progression." (PMID 37834191, 2023). "However, from another perspective, FN1, PRKACA were enriched in cancer pathways in this work, indicating that stemazole may affect the growth of hNSCs, instead of tumour cells, with a positive side." (PMID 35741576, 2022). "The analysis further revealed a total of tumor antigens including FAM134B, ALDH3A2, SAV1, RORC, and FN1, which were considered as significant candidates for the MESO-mRNA vaccine that could have immune provocative effects and be both presented and processed by APCs for a tumor response induction." (PMID 35893817, 2022). "Since FN1 is well-known as a mesenchymal indicator that has been reported to be involved in PTN in angiogenesis, the induction of FN1 or PTN mediated by lncRNA OIP5-AS1 in response to doxorubicin might contribute to chemoresistance accompanied by EMT induction and tumor metastasis." (PMID 36499136, 2022). "Therefore, it can be speculated that FN1 and CLDN7 proteins may mediate tumor progression through the network interaction with LCN2 and MMP9." (PMID 36211450, 2022). "Moreover, they showed that POSTN, FN1, VCAN, and pro-collagen-I (PCOL-I, newly synthesized COL-I) colocalize in extracellular strand and ring structures, visible inside the metastases and at the tumor-stroma interface." (PMID 34858485, 2021). "Instead, tumor-specific and context-dependent activation of subset of genes with distinct functions (e.g., SPARC, FN1, MMP7, ZEB1, ECM1) synergistically promoting, for example, collective cell migration upon interaction with the stromal microenvironment, may represent a more likely scenario." (PMID 34036938, 2021).
tumor (continued). "Additionally, FN1 was shown to induce MMP2 and MMP9 expression during the malignant progression of human cancers in previous studies, which was conducive to tumor migration, invasion, angiogenesis, and intravasation." (PMID 34758823, 2021). "Upregulated type I collagen, fibronectin (FN1) and other ECM proteins in breast cancer and upregulated collagens, non-collagen glycoproteins and proteoglycans in hepatocellular carcinoma suggest that the expression and component changes in the ECM are crucial indicators of tumor progression." (PMID 32236620, 2020). "In fact, these cells are reprogrammed to cancer-associated fibroblasts (CAFs) because tumor EVs transport active molecules, such as transforming growth factor beta (TGF-β), fibronectin-1 (FN1), and tissue transglutaminase (tTG) and may promote tumor progression and cancer cell invasion." (PMID 31281356, 2019). "Some of these proteins are key components of cell-cell or cell-matrix adhesion and includes annexin and integrins such as ANXA1, ANAX2, ITGB1, ITGA3, FN1, CTNNB1, APOH which interplay may activate exosome and leukocyte adhesion to tumor cells to limit tumor growth." (PMID 30111323, 2018). "Additionally, we detected that Sch B may play an anti-tumor role by down-regulating FN1 protein, but the specific regulatory mechanism is not yet clear." (PMID 40223922, 2025). "In addition, epithelial cells specifically interacted with mCAFs through the LAMININ, COLLAGEN, FN1, and MDK pathways, suggesting that in the tumor group, epithelial cells may promote cell proliferation and migration by attracting and recruiting mCAFs into the tumor microenvironment." (PMID 41187171, 2025). "For example, gene expression levels of COL1A1, COL6A3, and FN1 in CAFs as well as COL4A1 and COL4A2 in Angiogenic_EC were correlated with the proportion of the Cancer_Malig subtype in BC and CRC, indicating these pEMT tumor cells might be regulated by COL1A1 in CAFs and COL4A1 in Angiogenic_EC." (PMID 38002057, 2023). "Although experimentally we could not consider all the genes which showed significantly altered expression in recurrent vs nonrecurrent tumors, FN1 and ITGα3 both clearly impacted cell migration, hinting at roles which may be related to cellular mechanisms of tumor recurrence." (PMID 34791326, 2022). "Finally, FN1 was identified as the hub gene, and the upregulation was negative with tumor purity, suggesting that patients expressing high levels of FN1 may not respond to the mRNA vaccine." (PMID 35893817, 2022). "Genes that encoded extracellular matrix (ECM) components, such as COL1A1, COL1A2, LUM and FN1, were specifically expressed by fibroblasts, suggesting that the ECM in the NPC microenvironment was highly complex and might interact with surrounding tumor and stromal cells via integrin signaling." (PMID 33750785, 2021). "Here, the expression of COL5A3, FN1, and NOTCH3 was more specific to α-SMA-positive stromal cells rather than tumor cells, while IGFBP3 was overexpressed in both tumor and stroma in comparison to adjacent non-tumor tissues." (PMID 40522948, 2025). "Further analysis revealed a trend between connective tissue and tumor area, where FAP has a reverse relation with FN1 on tissue location, which is in accordance to the negative correlation between FAP and FN1 in TCGA seq data on FAPhigh TC cells." (PMID 41233863, 2025). "High FN1 expression in GC cells was related to poor prognosis, and high FN1 expression in the ECM did not predict overall survival (OS) and was correlated with tumor progression." (PMID 38737262, 2024). "Knockdown of POSTN, but not FN1, significantly slows the migration rate of ALK/MYCN tumor cells in filling the wounded area." (PMID 38451815, 2024). "The antitumour efficacy of bispecific antibodies plus talazoparib was not improved in the tumours that were insensitive to EGFR blockade, corresponding to the high expression of VIM and FN1 genes and relatively low expression of CDH1 and CLDN7 genes." (PMID 37441599, 2023).
tumor (continued). "FN1 and ITGA5 also play an important role in tumor angiogenesis, although the mode of action has not been elucidated." (PMID 35216235, 2022). "We found that FN1 and CD276 showed significantly higher expression in tumor sites than in the adjacent no-tumor samples (P < 0.05)." (PMID 35141255, 2021). "In order to assess FN1 correlation with CD276, we analyzed FN1 and CD276 expression in tumor sites and the adjacent no-tumor samples." (PMID 35141255, 2021). "The analysis of the corresponding tumor and non-tumor samples also revealed upregulation of COMP, matrix proteins such as COL5A1, COL11A1, and FN1, and genes of the Wnt pathway (WNT7B, FZD10, SFRP2), while PLCB1, CAMK2B, PLCB4 and WIF1 are downregulated." (PMID 33227073, 2020). "A further study conducted in our laboratory on a gamma-irradiated resistant oral keratinocyte cell line demonstrated that the downregulation of PLAU, FN1 and CDCA5 appeared to be indicators of the tumour being resistant to radiation therapy (data not shown)." (PMID 31443700, 2019). "The Mes tumor subtype predominantly expresses fibroblastic/mesenchymal genes, such as PDGFRA, VCAM1, ZEB1, TWIST1; and extracellular matrix genes, including collagen and FN1 (bolded genes are overlapping with our negative prognostic signature)." (PMID 36555638, 2022). "Hence, although FN1 and CDH1 are presumably not the key markers involved, these findings supported the view that the role of IGF2BP1 in promoting tumor cell migration and sustaining mesenchymal-like cell morphology involves the upregulation of LEF1 and SNAI2." (PMID 23677615, 2013).
cancer (682 papers, 1996 to 2026). A tumor composed of atypical neoplastic, often pleomorphic cells that invade other tissues. "We investigated five single-nucleotide variants (SNVs) of the FN1 gene in female reproductive organ cancers." (PMID 42196282, 2026). "Regarding T cells, cancer-associated fibroblast–derived (CAF-derived) fibronectin 1 (FN1) binds the CD44 receptor on T cell surfaces." (PMID 41514658, 2025). "Further analysis of ligand-receptor pairs revealed that VTN-(ITGAV + ITGB5), SEMA4D-PLXNB2, GAS6-TYRO3, and FN1-(ITGA3 + ITGB1) were more prevalent in high-risk cancer cells." (PMID 41034991, 2025). "In the context of solid tumors, FN1 has been demonstrated to play a pivotal role in various hallmark features of cancer, including proliferation, migration, invasion, angiogenesis, metastasis and epithelial-mesenchymal transition." (PMID 41488007, 2025). "Elevated FN1 expression has been linked to poor prognosis in cancers such as breast, lung, and gastric." (PMID 39833941, 2025). "The identification of FN1 regulation, along with the associated cancer-related pathways, offers potential mechanistic insights into the cellular responses to FB1 and HFB1." (PMID 41068355, 2025). "FN1 was proposed as a biomarker for various cancers, and its overexpression was linked to a poor prognostic and reduced patient survival." (PMID 41241706, 2025). "Among the top four upregulated DEGs, Chil3 is linked to immune function, whereas Fn1, JamL, and Ddit4 are associated with cancer." (PMID 40206211, 2025). "Earlier studies have also reported the association of COL1A1, COL1A2, COL3A1, and FN1 expression with OS in different other cancer patients." (PMID 38913913, 2024). "Fibronectin (FN1, SE = 2.0) assembled by CAFs mediates CAFs-cancer cells association and directional migration." (PMID 38892190, 2024). "FN1 exhibited a positive connection with cancer-associated fibroblasts and M2 macrophages while demonstrating a negative correlation with activated dendritic cells." (PMID 38610959, 2024). "PRPF8 overexpression directly influences cancer aggressiveness and alters cancer-related splicing variants, particularly fibronectin 1, a glycoprotein found in the extracellular matrix." (PMID 36609600, 2023). "Another particularly compelling example of a similarly misleading and likely artifactual fusion is COL1A1::FN1, which is detected as prevalent in cancer-associated fibroblast cell lines." (PMID 37323575, 2023). "Inhibition of ECM components, remodeling enzymes, blockers for cell surface receptors as integrins that bind FN1, or targeting cancer-associated fibroblasts are other alternatives for cancer treatment." (PMID 36146635, 2022). "Our data indicated that LSECtin downregulates the expression of STAT1 through the circFBXL4/miR-146a-5p axis, which ultimately leads to increased expression of FN1/CHD4 resulting in an increased risk of cancer." (PMID 35821222, 2022). "Fibronectin 1 (FN1) was shown to be expressed by leading invasive cancer cells and was linked to poor metastasis-free and overall survival in breast cancer." (PMID 35042889, 2022). "Among these genes, the most relevant gene was FN1 (encoding fibronectin) (r = 0.734, P < 0.0001), which is known to play an extremely important role in both focal adherence and cancer-related metastasis, and was chosen for further mechanistic study." (PMID 33738254, 2021). "The verified universal EV marker ITGB3 serves as a receptor for components of the ECM, including FN1, and plays roles in the progression of different cancer-associated processes, including initiation, proliferation, survival, migration, and invasion." (PMID 32916986, 2020). "As a high molecular weight glycoprotein, recent evidence has shown that FN1 is associated with a variety of cancers, and it is also involved in the invasion and migration of GC." (PMID 32908877, 2020).